CBL (Cbl proto-oncogene)
Diseases named in the same sentence as CBL in open-access papers (continued):
Sharing a sentence is not in itself a finding about the gene and the disease.
melanoma (continued). "Here, we studied the role of Casitas B-lineage lymphoma (c-CBL), an E3 ubiquitin ligase, in human melanoma." (PMID 27472394, 2016). "In-situ c-CBL immunoreactivity was quantified in clinical melanoma and benign nevi tissue sections using the Nuance multispectral imaging system." (PMID 27472394, 2016). "Taken together, we have provided evidence that c-CBL plays a role in melanoma cell proliferation, migration and invasion as well as inhibition of the FAK-GRB2-SRC nexus." (PMID 27472394, 2016). "Employing quantitative real-time PCR and Western blot analysis in a panel of human melanoma cell lines (A375, G361, Hs-294T, SK-Mel-2, SK-Mel-28 and 451Lu), we found that c-CBL is strongly expressed in human melanoma cells at the mRNA and protein levels." (PMID 27472394, 2016). "In summary, although there was some variation among the samples, c-CBL was found to be uniformly expressed by all melanoma cell lines and lesional tissue samples." (PMID 27472394, 2016). "In summary, we have shown that c-CBL plays a supportive role in the proliferation, migration and invasion of human melanoma cells." (PMID 27472394, 2016). "In this study of human melanoma, we determined the expression and functional consequences of inhibiting the proto-oncogenic E3 ubiquitin ligase, c-CBL." (PMID 27472394, 2016). "To determine the functional significance of c-CBL in melanoma, we performed knock-down of c-CBL using siRNA." (PMID 27472394, 2016). "In immunoblots, most of the melanoma lines showed prominent c-CBL expression with all the three antibodies." (PMID 27472394, 2016). "We checked the expression level of c-CBL in a panel of human melanoma cell lines using three different monoclonal antibodies reactive against different regions of the c-CBL protein (detailed in the method section)." (PMID 27472394, 2016). "In malignant melanoma, CBL is negatively correlated with miR-155 levels." (PMID 39130630, 2024). "Finally, SPRY2 (Bladder), CBL (Endometrial), TGFA (Melanoma) and GAB2 (Non-small cell lung) genes have high risk rate and low survival rate." (PMID 34764329, 2021). "DEG analysis further revealed upregulation of genes SPRY2 (Bladder), and GAB2 (Non-small cell lung) and downregulation of genes CBL (Endometrial), TGFA (Melanoma) were associated with low survival rate and high risk of death as measured by survival probability and AUC score." (PMID 34764329, 2021). "Based on our novel findings, additional studies are warranted to further delineate the function of c-CBL in melanoma and to determine whether targeting it will have therapeutic benefit." (PMID 27472394, 2016). "We also checked the clonogenic potential of melanoma cells with c-CBL knock down." (PMID 27472394, 2016). "In this report, we studied the role of the ring finger ubiquitin E3 ligase, c-CBL, in melanoma." (PMID 27472394, 2016). "We knocked down c-CBL expression via electroporation of c-CBL siRNA (si c-CBL) into melanoma cells." (PMID 27472394, 2016). "Next, we confirmed intracellular c-CBL immunoreactivity in melanoma cells via flow cytometry." (PMID 27472394, 2016). "Compared to benign nevi, melanomas showed an overlapping range of c-CBL immunoreactivity." (PMID 27472394, 2016). "Consistent with our results in melanoma, c-CBL protein has been shown to be overexpressed in prostate, gastric, pancreas, lung, primary colorectal cancers, glioma, myeloid, acute lymphoblastic leukemia, chronic lymphocytic leukemia, and cutaneous T-cell lymphoma." (PMID 27472394, 2016). "Interestingly, targeting CBL E3 ligases may also have synergistic effects in certain tumor cell types, such as melanoma, where c-CBL has recently been shown to promote tumor growth and mobility in part via the focal adhesion kinase (FAK)-GRB2-SRC nexus." (PMID 29794999, 2018). "Next we determined whether c-CBL affects the migration of melanoma cells." (PMID 27472394, 2016).
melanoma (continued). "After Survival Analysis we concluded that four genes (SPRY2-for Bladder cancer, CBL-for Endometrial cancer, TGFA-for Melanoma and GAB2 for Non-small cell lung cancer) were the Biomarkers for Nitroglycerin." (PMID 34764329, 2021). "These are EGFR, ERRFI1, IL6, JAK2, PLXNC1, RGL3 which were found to be upregulated and CBL, CDC42, PIK3R3, STAT3, UBE2D2 and YWHAZ which were found to be downregulated; Melanoma has PLXNC1 as upregulated and TGFA as downregulated gene." (PMID 34764329, 2021). "We found that c-CBL knockdown resulted in reduced FAK, SRC and GRB2 protein expression in several melanoma cell lines." (PMID 27472394, 2016). "Further, cellular growth in other c-CBL knock-down melanoma cell lines was measured with a non-fluorescent viability reagent, Resazurin, which is reduced by viabile cells to fluorescent Resorufin (ex530nm/em 590nm) in the mitochondria." (PMID 27472394, 2016). "Clonogenic output of melanoma cells with c-CBL knock down resulted in reduced colonies compared to nonsense control." (PMID 27472394, 2016). "Our data demonstrate that the effects of c-CBL knockdown in melanoma, were accompanied by decreases in the protein and mRNA levels of FAK, SRC and GRB2, suggesting the involvement of the FAK-GRB2-SRC nexus in the consequences of c-CBL alteration." (PMID 27472394, 2016). "Contrary to our findings on c-CBL knock down in CTCL, down regulation of c-CBL in melanoma did not result in cellular death." (PMID 27472394, 2016).
non-small cell lung carcinoma (12 papers, 2011 to 2024). A group of at least three distinct histological types of lung cancer, including non-small cell squamous cell carcinoma, adenocarcinoma, and large cell carcinoma. "CBL has been shown to promote c-FLIPS degradation in non-small cell lung carcinoma cells via mTORC2-dependent signaling." (PMID 29374180, 2018). "However, disputes existed in the role of CBL played in the tumor, research showed that in non-small cell lung cancer, CBL downregulated PD-L1." (PMID 35027542, 2022). "This study also suggests that a combination of doxazosin and other EPHA2 inhibitors directed to inhibit the pertinent signaling components may be a novel therapeutic strategy for MPM and Non-small cell lung cancer patients who have either EPHA2 or CBL alterations." (PMID 31484920, 2019). "We also see Steiner nodes such as CBL and ITGB5, which have been shown to be involved in several models of non-small cell lung cancers, like the H358 cells." (PMID 28759592, 2017).
glioma (11 papers, 2016 to 2026). A benign or malignant brain and spinal cord tumor that arises from glial cells (astrocytes, oligodendrocytes, ependymal cells). "EGFRvIII, the most common variant in gliomas, also has a reduced interaction with CBL and thus impaired ubiquitination owing to hypophosphorylation of pY1045." (PMID 30544639, 2018). "Previous research has been observed that c-CBL mediates the migration and invasion of glioma cells, such as C6 and human A172 glioma cells, by exerting a negative regulatory effect on αPix." (PMID 39130630, 2024). "PTPRU knockdown also led to the increase of tyrosine pY in c-CBL, which further affects β-catenin and focal adhesion signals, and promotes the progression of glioma." (PMID 39130630, 2024). "In recent years, as research deepens, more and more ways of CBL affecting glioma have been discovered." (PMID 39130630, 2024). "Inhibition of CBL can significantly inhibit the formation of glioma cells." (PMID 39130630, 2024). "The association between CBL and EGFR offers a new way to study glioma." (PMID 39130630, 2024). "DECA may enhance glioma cell apoptosis by influencing the expression of CBL gene." (PMID 39130630, 2024). "In 2013, the study of Jingwen Zhang revealed that tissue transglutaminase (TTG) blocks the EGFR ubiquitination catalyzed by c-CBL through the interaction with c-CBL, which enhances EGFR signaling and thus promotes the formation of glioma." (PMID 39130630, 2024). "The top five scored genes (TAF1, TAFL1, CBL, CCNT1, and RMNT) were further analyzed in the glioma tissues samples in the CGGA database." (PMID 32322592, 2020). "In gliomas, ZC3H15 suppresses CBL expression, thereby enhancing EGFR protein stability." (PMID 41513632, 2026). "In A172 (human) and C6 (rat) glioma cells, c-CBL is not expressed, causing αPix accumulation and consequently promoting cell migration and invasion; this in contrast to other cell lines that do express c-CBL." (PMID 33665742, 2021).
chronic myelomonocytic leukemia (10 papers, 2011 to 2025). A myelodysplastic/myeloproliferative neoplasm which is characterized by persistent monocytosis, absence of a Philadelphia chromosome and BCR/ABL fusion gene, fewer than 20 percent blasts in the bone marrow and blood, myelodysplasia, and absence of PDGFRA or PDGFRB rearrangement. "We compared findings from CBL-mutated patients in the Austrian biodatabase for chronic myelomonocytic leukemia (ABCMML) with those in the CMML cohort recorded in cBIOPORTAL." (PMID 40569544, 2025). "We also searched for TET2, DNMT3A, ASXL1, EZH2, IDH1/2 and CBL gene families mutations, given their potential clinical importance in diseases closely associated with SM like primary myelofibrosis, chronic myelomonocytic leukemia (CMML) and others." (PMID 22905207, 2012).
colorectal cancer (10 papers, 2014 to 2024). A primary or metastatic malignant neoplasm that affects the colon or rectum. "According to subsequent investigations, the loss of c-CBL function notably enhanced the proliferation of nuclear beta-catenin and colorectal cancer (CRC) tumors, as observed in both cell culture and mouse xenotransplantation models." (PMID 39130630, 2024). "In order to gain a deeper understanding of the significance of c-CBL in colorectal cancer, we studied c-CBL expression levels in 22 patients with primary CRC." (PMID 39130630, 2024). "Regulated by Tyr371 phosphorylation, CBL inhibits the tumorigenesis of colorectal cancer via targeting Wnt/β-catenin." (PMID 33231565, 2020). "The ubiquitin ligases CBL and SKP2 were identified as candidate oncogenes, while the ubiquitin ligase FBXW7 is a bona fide tumor suppressor that is mutated frequently in breast and colorectal cancers." (PMID 24874471, 2014). "Both the partial deletion of c-CBL and the inactivation of tumor suppressive colorectal polyposis (APC) promote the occurrence and development of colorectal cancer." (PMID 39130630, 2024). "Together, the potential combined effect of modulation of macrophages via efferocytosis and T-cells via PD-L1 expression, prime a favorable tumor-microenvironment raising the importance of dysregulation of CBL, CBLB, XKR4 and ANO5 in colorectal carcinoma." (PMID 30429477, 2018).
prostate carcinoma (10 papers, 2008 to 2025). A carcinoma that arises from epithelial cells of the prostate gland. "The expression of CBL can induce the apoptosis of prostate cancer cells and has the effect of inhibiting cancer." (PMID 39130630, 2024). "In prostate cancer, c-CBL was shown to regulate tumor cell adhesion, migration, and degradation, and to act as an oncogenic prognostic marker correlating with poor clinical outcome." (PMID 27472394, 2016).
myeloid leukemia (8 papers, 2012 to 2024). A clonal proliferation of myeloid cells and their precursors in the bone marrow, peripheral blood, and spleen. "Consistent with the expression of CBL and CBL-B in the hematopoietic system, mutations in CBL, and rarely CBL-B, are associated with certain forms of myeloid leukemia, with as many as 15% cases of JMML due to mutations in CBL." (PMID 27449297, 2016). "We knocked out CBL in K562 cells, an immortalized myelogenous leukemia cell line overexpressing FLT3, and stimulated these cells with FLT3LG at various time points." (PMID 39403923, 2024). "Taken together, our results support the notion that mutant CBL‐expressing myeloid leukaemias are highly sensitive to available FLT3 inhibitors and that this effect can be significantly augmented by optimum inhibition of SYK kinase." (PMID 31943762, 2020). "We found that miRs-31 and -155, which were downregulated in our setting, potentially target CBL, which is involved in cancer initiation and progression and was originally discovered as an oncogene which induces B-cell and myeloid leukemias in mice." (PMID 22511990, 2012).
glioblastoma (6 papers, 2016 to 2025). The most malignant astrocytic tumor (WHO grade IV). "Within the cellular pathway, glioblastoma (GBM) cells employ Cool-1/β-pix to obstruct the regular activation of the c-CBL ubiquitin ligase through the redox/Fyn/c-CBL pathway." (PMID 39130630, 2024). "We performed further detailed analyses on samples from three specific studies on patients with glioblastoma multiforme (n=136), lung adenocarcinoma (n=230) and head and neck squamous cell carcinoma (n=279), where EGFR protein levels were compared with c-CBL transcript levels." (PMID 27612423, 2016).
lymphoma (6 papers, 2018 to 2023). A malignant (clonal) proliferation of B- lymphocytes or T- lymphocytes which involves the lymph nodes, bone marrow and/or extranodal sites. "TAK-659 completely inhibits phosphorylation of CBL in LMP2A/MYC lymphoma cells." (PMID 30135222, 2018).
Obesity (6 papers, 2010 to 2024). Accumulation of substantial excess body fat. "We previously reported that CBL signalling is impaired in animal models of insulin deficiency and in obesity." (PMID 29114012, 2018). "When the obesity causal genes were overlapped with the fasted and fed networks, 7 genes (ADA, BBS5, CBL, CCND3, FASN, FTO and SCARB1) overlapped with PER1's downstream genes in the fed network (Fisher's Exact Test p-value = 0.037)." (PMID 20168994, 2010).
autoimmune disease (5 papers, 2019 to 2025). A disorder resulting from loss of function or tissue destruction of an organ or multiple organs, arising from humoral or cellular immune responses of the individual to their own tissue constituents. "The gene involved in regulating CBL function in T cell receptor signaling pathway, and mutations in this gene may be linked to a range of autoimmune diseases rheumatoid arthritis." (PMID 37377963, 2023).
hepatocellular carcinoma (5 papers, 2019 to 2024). A malignant tumor that arises from hepatocytes. "Conversely, the overexpression of CBL counteracts the inhibitory effect of miR-486-5p on the proliferation and migration of hepatocellular carcinoma (HCC) cells." (PMID 39130630, 2024). "In hepatocellular carcinoma, miR-486-5p overexpression hindered cell proliferation and motility through repressing CBL." (PMID 33954256, 2021).
Insulin resistance (5 papers, 2015 to 2024). Increased resistance towards insulin, that is, diminished effectiveness of insulin in reducing blood glucose levels. "Along with the upregulation of the CBL signaling pathway, the evidence indicates that OLE may also downregulate insulin resistance." (PMID 37445596, 2023).
colon cancer (4 papers, 2019 to 2024). "Therefore, the increased expression of CBL in the early stages of colon cancer could potentially be associated with prognosis." (PMID 39130630, 2024). "This co-localized MUC1/CIN85/CBL complex is suspected to play a significant role in the promotion and progression of colon cancer." (PMID 39130630, 2024). "Consequently, the outcomes of the study imply that ephrinA5 inhibits the progression of colon cancer by promoting the degradation of EGFR as mediated by c-CBL." (PMID 39130630, 2024). "It has been reported that miR-155 promoted the migration of colon cancer cells by targeting CBL." (PMID 32675943, 2020). "In a colon cancer cell line model, the presence of ephrinA5 exerted an inhibitory effect on EGFR by facilitating c-CBL-mediated EGFR ubiquitination and subsequent degradation." (PMID 39130630, 2024). "Enhanced CBL activity leads to the downregulation of EGFR expression and the inhibition of colon tumor cell proliferation." (PMID 39130630, 2024). "Enhanced CBL activity is known to result in the down-regulation of EGFR expression and inhibition of proliferation in colon tumor cells." (PMID 31324852, 2019).
myelofibrosis (4 papers, 2015 to 2023). A partial or complete replacement of the bone marrow stroma by fibrous tissue. "Moreover, RAS/CBL mutations predict resistance to JAK inhibitors in myelofibrosis and are associated with poor prognostic features." (PMID 37317963, 2023).
ovarian carcinoma (4 papers, 2019 to 2025). A malignant neoplasm originating from the surface ovarian epithelium. "Initial research has indicated that in ovarian cancer, CBL may function as a proto-oncogene involved in signal transduction and the regulation of tyrosine phosphorylation." (PMID 39130630, 2024).
Splenomegaly (4 papers, 2020 to 2024). Abnormal increased size of the spleen. "Clinically, CBL mutations were associated with increased bone marrow blasts at diagnosis, leukocytosis and splenomegaly, similar to patients harboring NRAS or KRAS mutations." (PMID 39298477, 2024). "Clinically, CBL mutations were associated with a more proliferative phenotype evidenced by increased bone marrow blasts, leukocytosis and splenomegaly, similar to other RAS pathway mutations such as KRAS, NRAS and PTPN11." (PMID 39298477, 2024). "CBL variants were associated with a myeloproliferative phenotype, including higher white cell count and splenomegaly with many patients having increased blasts at diagnosis, similar to patients with other RAS pathway mutations." (PMID 39298477, 2024). "The second patient in our series had a germline Y371H CBL mutation, and given persistent massive splenomegaly, thrombocytopenia, and rising AMC, underwent HSCT." (PMID 39123476, 2024). "10/11 (90.9%; P = 0.03) patients with CBL variants presented with splenomegaly." (PMID 39298477, 2024).
acute leukemia (3 papers, 2022 to 2024). A clonal (malignant) hematopoietic disorder with an acute onset, affecting the bone marrow and the peripheral blood. "Although uncommon, KMT2A::CBL fusion has been reported in both pediatric and adult acute leukemias, including AML and ALL." (PMID 38643442, 2024). "The breakpoints of the KMT2A and CBL genes in Case #3 were different from those in acute leukemia, which should be validated by other methods like RNA-seq." (PMID 35991838, 2022). "Acute leukemias with KMT2A::CBL rearrangements have not been reported in many studies." (PMID 38643442, 2024).
anemia (3 papers, 2010 to 2025). A reduction in the number of red blood cells, the amount of hemoglobin, and/or the volume of packed red blood cells. "Mutations in ASXL1 and CBL were frequent in refractory anemia with excess of blasts." (PMID 20678218, 2010).
diabetes (3 papers, 2013 to 2024). "It has been reported that CBL might alleviate endothelial dysfunction in patients with diabetes mellitus by inactivating the JAK2/STAT4 signalling pathway." (PMID 36726727, 2023).
head and neck squamous cell carcinoma (3 papers, 2016 to 2017). A squamous cell carcinoma that arises from any of the following anatomic sites: lip and oral cavity, nasal cavity, paranasal sinuses, pharynx, larynx, and salivary glands. "MET is frequently overexpressed in head and neck squamous cell carcinoma (HNSCC) and degraded by c-CBL E3-ubiquitin ligase." (PMID 27244893, 2017).